FGL2 (fibrinogen like 2)
Diseases named in the same sentence as FGL2 in open-access papers (continued):
Sharing a sentence is not in itself a finding about the gene and the disease.
tumor (continued). "On the contrary, FGL2 could increase the levels of tumoricidal cells such as CD8+ T cytotoxic cells, natural killer (NK) cells in the tumor microenvironment." (PMID 32206449, 2020). "Going forward, an intriguing proposition that warrants further enquiry is the direct negative impact of Treg-derived FGL2 on anti-tumor CD8+ T-cells independent of DCs and Tconv cells." (PMID 33375291, 2020). "Notably, we found that FGL2 expression correlated more strongly with TAM and M2 macrophage levels in normal tissues than in ESCA tumor tissues." (PMID 33323552, 2020). "Further investigation is required to assess the potential of FGL2 as a therapeutic target and immunomodulator in ESCA, and to determine whether FGL2 levels in peripheral blood can be used as a tumor marker for the early screening and diagnosis of this disease." (PMID 33323552, 2020). "FGL2 knockout in tumor cells did not affect tumor-cell proliferation in vitro or tumor progression in immunodeficient mice but completely impaired GBM progression in immune-competent mice." (PMID 30683885, 2019). "Our study suggests that one possible reason for this is the presence of FGL2 in tumor cells, which inhibits CD103+ DC differentiation and has not been previously accounted for." (PMID 30683885, 2019). "In line with previous studies, up-regulation of FGL2 mRNA was observed in tumor tissues, compared to directly adjacent non-tumor tissues." (PMID 30419833, 2018). "The relative expression of FGL2 mRNA was significantly up-regulated in tumor tissues compared to adjacent non-tumor tissues (P = 0.043)." (PMID 30419833, 2018). "In tumors from WT hosts, Fgl2 was detected in the tumor lysate, whereas Fgl2 was undetectable in the tumor lysate from Fgl2–/– mice, suggesting that B16 cancer cells are not a cellular source of Fgl2." (PMID 40125553, 2025). "However, the increased frequency of FcγRIIB+CD8+ T cells at the tumor coupled with the increased secretion of Fgl2 by CD11b+ cells at the tumor further amplifies this negative feedback loop, resulting in a curtailed T cell antitumor response." (PMID 40125553, 2025). "Further elucidating the detrimental impact of FcγRIIB+CD8+ T cell death, linear regression showed that the frequency of FcγRIIB+CD8+ T cells was negatively associated with tumor size in WT HSC–reconstituted mice (R2 = 0.58, P = 0.0101) but not in Fgl2–/– HSC–reconstituted mice." (PMID 40125553, 2025). "Surprisingly, the tumor itself is not the major cellular source of Fgl2." (PMID 40125553, 2025). "Fgl2 selectively regulates WT but not Fcgr2b–/– tumor-specific CD8+ T cells in vivo." (PMID 40125553, 2025). "Macrophage-secreted Fgl2 induces apoptosis of WT but not Fcgr2b–/– tumor-specific CD8+T cells." (PMID 40125553, 2025). "Regulation of FcγRIIB+CD8+ T cells is dependent on host Fgl2 and not tumor-derived Fgl2." (PMID 40125553, 2025). "Furthermore, FGL2 knockdown hinders the activation of PAR2 and weakens downstream JNK phosphorylation, resulting in tumor cell cycle arrest, reduced expression of vascular endothelial growth factor (VEGF) and IL-8, and inhibition of tumor proliferation and angiogenesis." (PMID 38816776, 2024). "Therefore, we investigated the evolutionary history of cancer associated gene sequences across 384 mammalian taxa, to detect signatures of selection across categories of oncogenes (GRB2, FGL2 and CDC42), tumour suppressors (LITAF, Casp8 and BRCA2) and immune genes (IL2, CD274 and B2M)." (PMID 38773187, 2024). "Given the increase in B16F10 tumour-infiltrating DCs, co-stimulatory molecules on DCs, and activated (CD25+, TIGIT+) CD4 T cells, we predicted DC and T cell interactions might play a role in prolonging survival in Fgl2−/− mice." (PMID 38191799, 2024).
tumor (continued). "In the IMvigor210 cohort, lower FGL2 expression was observed in the desert phenotype (patients with this phenotype were less likely to benefit from immunotherapy), IC0 (immune cells with the lowest PD-L1 values), and TC0 (tumor cells with the lowest PD-L1 values) groups." (PMID 38903931, 2024). "Therefore, we sought to determine how FGL2 expressed in immune cells in the TME might promote immunosuppression and how it might influence tumour progression and survival." (PMID 38191799, 2024). "However, it should be noted that we did observe decreased CD31 + (endothelial) cells in the B16F10 tumours implanted in Fgl2−/− mice, suggesting the absence of FGL2 also decreased vascularization of the tumour." (PMID 38191799, 2024). "In this study, only B16F10 tumour-bearing mice had prolonged survival in the absence of FGL2." (PMID 38191799, 2024). "In an agreement with the survival outcomes, FGL2 expression was associated with several favourable risk factors for GIST recurrence, such as a low cell proliferation rate, small size and the absence of tumour necrosis, and also with low TIL counts." (PMID 35029030, 2022). "Interestingly, FGL2 is primarily but not exclusively expressed in the immune cells, tumor cells and tumor stroma of the TME, and can also be produced by hematopoietic cells." (PMID 33323552, 2020). "However, the numbers of MDSC and M2 macrophages in tumor and paracancerous tissue were not altered by Fgl2 knockout." (PMID 31409352, 2019). "Therefore, FGL2 expression in the tumor cell but not in the host is required for tumor progression in immune-competent mice." (PMID 30683885, 2019). "Moreover, FGL2 knockdown delays HCC growth and tumour angiogenesis." (PMID 28978925, 2017). "To further understand the molecular mechanism by which the FGL2-blocking scFv induces CD69+CD8+ TM cell generation, we analyzed CyTOF data for chemokine receptors (i.e., CCR2, CXCR3, CXCR2, and CX3CR1) that may affect T cell infiltration and recruitment to tumor sites." (PMID 36759517, 2023). "Therefore, future GM-CSF-based cancer vaccines may require the use of FGL2 depletion or blockade or patient stratification based on the absence of tumor-expressed FGL2." (PMID 30683885, 2019). "Furthermore, we examined the expression of FGL2 mRNA in tumor and adjacent non-tumor tissues." (PMID 30419833, 2018). "However, the reason for the upregulation of FGL-2 in tumor cells is not clear." (PMID 25303152, 2014). "Taken together, these data support the conclusion that regulation of FcγRIIB-competent tumor-specific CD8+ T cells, but not Fcgr2b–/– CD8+ T cells, are uniquely regulated via Fgl2." (PMID 40125553, 2025). "After coculture of CD11b+ cells isolated from a tumor-challenged mice with OVA-specific CD8+ T cells, FcγRIIB-competent CD8+ T cells were selectively driven to apoptosis by WT but not Fgl2–/– CD11b+ cells, a phenomenon that we did not observe in Fcgr2b–/– OVA-specific CD8+ T cells." (PMID 40125553, 2025). "In the B16F10 and STOSE models, where blocking FGL2 did not prolong survival, increased presence of TIGIT+ Tregs, which do express high amounts of FGL227, may have impeded tumour elimination." (PMID 38191799, 2024).
cancer (37 papers, 2010 to 2026). A tumor composed of atypical neoplastic, often pleomorphic cells that invade other tissues. "This is a major finding since it presents a new mechanism by which FGL2, an established procoagulant, immunomodulator and cancer associated protein, is introduced into the peripheral blood." (PMID 37200306, 2023). "This indicates that FGL2 is involved in controlling the immunopathological damage through PD-1 signaling, which is associated with various types of cancer." (PMID 30419833, 2018). "In contrast, FGL2 may play a role in accelerating cancer progression by activating cancer-associated fibroblasts in the TME or by inducing epithelial macrophage transformation." (PMID 39575432, 2024). "As expression of FGL2 has been shown to be associated with other diseases including HIV, SARS, and cancer, measurement of sFGL2 levels and development of reagents that interfere with FGL2 may have even broader applicability." (PMID 23908776, 2010). "Our findings unveil a novel exosome-dependent mechanism through which tumors systemically educate MDSCs, establishing the Fgl2-FcγRIIB axis as a promising broad-spectrum target for cancer immunotherapy." (PMID 41875310, 2026). "Elevated systemic levels of Fgl2 have been observed in the settings of hepatitis, renal injury, endometriosis, and certain cancer types." (PMID 40125553, 2025). "For example, in chronic viral infections and cancers, FGL2 induces apoptosis through paracrine mechanisms, contributing to CD8+ T cell exhaustion." (PMID 40978140, 2025). "The translational value of these studies is underscored by the expression of Fgl2 in myeloid cells across 10 cancer types in humans." (PMID 40125553, 2025). "To measure Fgl2 at the protein level in the B16 mouse model, we challenged WT mice with B16 cancer cells for downstream immune profiling." (PMID 40125553, 2025). "Coupled together, these data allow us to conclude that across various cancer types, myeloid cells are a considerable source of Fgl2 at the RNA level in humans." (PMID 40125553, 2025). "Herein, FGL2 was found to be positively correlated with the critical steps of the cancer-immunity cycle." (PMID 38903931, 2024). "In conclusion, targeting FGL2 is a promising cancer treatment strategy alone and in combination immunotherapies." (PMID 38191799, 2024). "An analysis of data from The Cancer Genome Atlas found an inverse correlation between FGL2 expression and GBM patient survival." (PMID 36759517, 2023). "Since accumulating evidence has demonstrated the potential of FGL2 as a therapeutic target and biomarker, the secretion of FGL2 by activated platelets at the cancer environment should also be taken into account in cancer research and therapeutics." (PMID 37200306, 2023). "In COAD, FGL2 can be used as a new prognostic marker and an effective therapeutic target, and the overexpression of FGL2 enhances cancer cell invasion, induces epithelial mesenchymal transition (EMT), and promotes COAD invasion and metastasis." (PMID 36387195, 2022). "We found that FGL2, a fibrinogen‐related protein, is expressed frequently in GISTs as compared with many other human cancers, and it is expressed also in the interstitial cells of Cajal." (PMID 35029030, 2022). "According to the database, many types of cancer express low FGL2 mRNA levels, but high FGL2 expression is characteristic for GIST." (PMID 35029030, 2022). "We found that GISTs expressed FGL2 mRNA highly compared to other types of cancer in a large human cancer transcriptome database." (PMID 35029030, 2022). "A growing body of investigations highlights that members of FREP superfamily, such as fibrinogen-like protein-1 (FGL1), and fibrinogen-like protein-2 (FGL2), play pivotal roles in cancer and in modulating immune cell functions." (PMID 33867830, 2021).
cancer (continued). "In this review, we overview the current understandings of the roles of FGL1 and FGL2 in cancer microenvironment, and review the roles of FGL1 and FGL2 as potential immunotherapeutic targets for cancer therapy." (PMID 33867830, 2021). "For example, cancer cells secrete Fibrinogen-like Protein 2 (FGL2) that antagonizes GM-CSF and blocks the cDC1 activation, escaping from immune-control." (PMID 33804731, 2021). "Next, we used cBioPortal to evaluate the correlations between the levels of FGL2 and the cancer-promoting cytokines measured above (IL-10, MMP9, CCL5, TIM-3, IL-13, VCAM1, M-CSF and FGF-7) in ESCA tissues." (PMID 33323552, 2020). "Fibrinogen-like protein 2, FGL-2, was reported to be overexpressed in various cancer tissues, where it acts as a transmembrane prothrombinase." (PMID 25303152, 2014). "Myeloid cells are a predominant cellular source of Fgl2 in humans with cancer." (PMID 40125553, 2025). "Across 10 different cancer types, Fgl2 was robustly expressed in the sorted myeloid population." (PMID 40125553, 2025). "Thus, the therapeutic efficacy of using Fgl2-blocking antibodies has recently been explored in the context of viral infection and cancer." (PMID 40125553, 2025). "However, in all these studies the assumption was that FGL2 was expressed by the cancer cells and, in mechanistic studies, cancer cells were engineered to overexpress FGL2." (PMID 38191799, 2024). "While many previous studies have suggested FGL2 expression by cancer cells may result in a less favourable prognosis, we found that Fgl2 was expressed in the macrophage/monocyte and DC populations with minimal expression in the cancer (epithelial) cells." (PMID 38191799, 2024). "The expression of FGL1 and FGL2 in 20 types of cancers and their normal counterparts were measured." (PMID 38903931, 2024). "CD93 and FGL2 were recently highlighted as promising CAR‐T cell targets in AML or other cancers." (PMID 39054581, 2024). "We assumed that these different results in various types of cancer might be due to the different functions of the mFGL2 and sFGL2 subtypes, which should be assessed when studying the role of FGL2 in other cancers." (PMID 39575432, 2024). "Furthermore, samples from the UALCAN database were analyzed based on sample type, molecular subtype, lymph node metastasis, and cancer stage, revealing a significantly lower FGL2 expression in BLCA compared to normal controls." (PMID 38903931, 2024). "Human cancer metastasis database (HCMDB) was analyzed that miR-20a-5p by targeting FGL2 and miR-139-5p by targeting STC1 could play a role mainly in liver metastatic CRC." (PMID 38036953, 2023). "FGL2 is an important pleiotropic immunomodulatory cytokine discovered in recent years, which in cancer achieves immunosuppression by inhibiting antigen-presenting cells (APCs), suppressing T cell proliferation, inducing macrophage polarization to M2 and inducing regulatory T cell (TREG) activity." (PMID 36313679, 2022). "FGL2 mediates a wide variety of immunological effects and sFGL2 is immunosuppressive, and could, therefore, promote cancer growth." (PMID 35029030, 2022). "These variable results may be due the different functions of mFGL2 and sFGL2, which needs to be considered when assessing the effects of FGL2 in cancer." (PMID 35029030, 2022). "We conclude FGL2 expression is high in GISTs compared to many other human cancers." (PMID 35029030, 2022). "The upregulation of FGL2 has been reported in different cancers." (PMID 33323552, 2020). "The biological functions of FGL2 may also vary in different types of human cancer." (PMID 35029030, 2022). "We speculated that FGL2 might play differential roles in distinct models of cancer." (PMID 32206449, 2020). "In brief, FGL2 might play different roles in different types of cancer models." (PMID 32206449, 2020). "In addition to cancer therapy, therapeutics targeting FGL2 may also prove useful in treatment of infectious disease." (PMID 26241231, 2015).
cancer (continued). "This work substantiates previous work from our laboratory demonstrating that the immunosuppressive cytokine, Fgl2, can bind FcγRIIB+CD8+ T cells in vitro and provides evidence that this phenomenon occurs in vivo in the setting of cancer." (PMID 40125553, 2025). "However, it has been reported that FGL2 in different cancer models may have inconsistent roles." (PMID 39575432, 2024). "We found that in many types of cancer, FGL2 is produced by immune and stromal cells in the TME, particularly monocytes and macrophages, and to a lesser extent, by T cells and DCs, while cancer cells have minimal FGL2 expression." (PMID 38191799, 2024). "The immune-modulatory functions of FGL2 relative to FGL1 are more extensively described, in general and in the context of cancer." (PMID 37115694, 2023). "We therefore studied the role of FGL2 exclusively produced by immune and stromal cells in the TME, in two models of cancer in which the role of FGL2 was not previously studied." (PMID 38191799, 2024). "No data exist regarding FGL-2 activity or expression in PBMC of normal individuals or patients with malignancy." (PMID 25303152, 2014). "Therefore, it is remarkable that a poorly immunogenic cancer model which did not respond to a complete knockout in FGL2 (Fgl2−/− mice) was able to survive significantly longer with the addition of an oncolytic virus to an FGL2-deficient background." (PMID 38191799, 2024). "Fgl2-expressing CD8+ T cells were contained almost entirely (p < 0.001) within the population of cells that express PD-1, a cell surface receptor that marks antigen-experienced and functionally exhausted CD8+ T cells in the context of cancer and chronic viral infection." (PMID 38902261, 2024). "Importantly, while some previous studies have proposed FGL2 expression in cancer cells, the commonly used antibody from Abnova (clone 6D9) shows a non-specific band in cell lines where FGL2 is not detectable by qPCR." (PMID 38191799, 2024). "The expression of Fgl2 is significantly higher in many cancers, including colon cancer, oesophageal cancer, gastric cancer, breast cancer, lung cancer, and cervical cancer, but weakly expressed or not expressed in normal tissues adjacent to cancer." (PMID 34975313, 2022). "However, Fibrinogen-like Protein 2 (FGL2), that is predominantly secreted by the cancer cells, may interfere with the induction of these immunostimulatory DCs." (PMID 32014107, 2020). "Finally, the role of FGL2 in many cancers has not yet been studied." (PMID 26241231, 2015). "However, the prothrombinase activity of FGL-2 in PBMC of cancer patients has not been studied yet." (PMID 25303152, 2014).